CCDC191 (coiled-coil domain containing 191)
Synonyms: KIAA1407
Tractability: PROTAC: ubiquitination databases record sites on it.
Gene: Protein-coding gene on chromosome 3 (113,964,137 to 114,056,594, reverse strand). Ensembl gene ENSG00000163617.
Subcellular location (Human Protein Atlas): Mitochondria
Genetic constraint (gnomAD): Loss-of-function variants: 77 observed, 90.45 expected, observed/expected ratio (o/e) 0.85, 90% interval 0.71 to 1.03. The upper end of that interval is the gene's LOEUF score, 1.03, which puts it in group 4 of 6, group 1 being the genes least tolerant of losing a copy. Missense variants: 814 observed, 941.83 expected, observed/expected ratio (o/e) 0.86, 90% interval 0.81 to 0.92. Synonymous variants: 296 observed, 332.34 expected, observed/expected ratio (o/e) 0.89, 90% interval 0.81 to 0.98.
Homologues: Orthologues: chimpanzee CCDC191 (98% identical), macaque CCDC191 (93% identical), rabbit CCDC191 (75% identical), dog CCDC191 (74% identical), pig CCDC191 (73% identical), guinea pig CCDC191 (68% identical), rat Ccdc191 (68% identical), mouse Ccdc191 (67% identical), tropical clawed frog ccdc191 (41% identical), zebrafish ccdc191 (32% identical), Drosophila melanogaster CG17258 (16% identical). Paralogues in human: SFI1 (12% identical).
Diseases named in the same sentence as CCDC191 in open-access papers:
CCDC191 is named in the same sentence as 2 diseases in open-access papers, as found by Europe PMC text mining. Sharing a sentence is not in itself a finding about the gene and the disease. The quoted sentences say what the papers report.
tumours (1 paper, 2021). "PR−/ER− cases demonstrated frequent loss of LNX1 and SNORA80A, and gain of ZNF4, STK24 and CCDC191; gain of CDK20 was common in PR-high tumours." (PMID 34079052, 2021).
CCDC191 also shares sentences with these, for which no sentence is quoted: cancer (1 paper).